IL21 (interleukin 21)
Diseases named in the same sentence as IL21 in open-access papers (continued):
Sharing a sentence is not in itself a finding about the gene and the disease.
Arthritis (23 papers, 2008 to 2025). Inflammation of a joint. "In this study, an induced deficiency in the receptor of IL-21 was sufficient to completely prevent the onset and subsequent development of arthritis in the K/BxN mouse model." (PMID 34638855, 2021). "Fifth, following items: the correlation of IL-21 rs6822844 polymorphism with the stages of arthritis; the protein expression level of IL-21 in different polymorphisms should also be added and be re-analyzed by meta in the future research." (PMID 31763680, 2020). "Although the presence of arthritis in ApoE−/− mice was associated with increased levels of G-CSF, KC/Gro-a and decreased levels of IL-21, IL-23 and MIP-2, the greatest change was observed in IL-6." (PMID 27287704, 2016). "In addition to its importance in T cell development, IL-21 has been implicated in B cell development and antibody production, processes relevant to RA and important in this experimental arthritis model as well." (PMID 28158305, 2017). "Its elevated secretion under various inflammatory states suggests a link with arthritis development, as IL21 binds to its receptor IL21R." (PMID 38728237, 2024). "Statistically significant positive linear correlations were found between the VAS for arthritis and both the serum IL-4 level (r = 0.470; p < 0.001) and the serum IL-21 level (r = 0.403; p < 0.01)." (PMID 37763102, 2023). "Cytokines level (members of IL-1 family, IL-6 and its receptor, IL-17, IL-20, IL-21, and IL-23) increases in early stages of arthritis and decreases during regression of inflammation." (PMID 35061737, 2022). "Further, in the experimental arthritis model, the blockade of IL-21/IL-21 receptor pathways significantly improved disease severity, suggesting an essential role of IL-21 in disease pathogenesis." (PMID 33673829, 2021). "Further studies on blocking IL-21 signaling by IL-21R/Fc reduced cytokine production and arthritis in animal models of CIA." (PMID 33515210, 2021). "Administration of IL-21 receptor Fc fusion protein (IL-21RFc), a neutralizing agent of IL-21 in the arthritis model, significantly diminished IL-6 and IL-17." (PMID 33673829, 2021). "This clearly attributes an important role of the IL-21/IL-21R axis in the very early stages of arthritis development." (PMID 34638855, 2021). "While high systemic IL-21 levels can partially overcome the regulatory effect of ethanol in arthritis, IL-21 does not only affect TFH cells." (PMID 32332730, 2020). "Myeloid cells of lymphatic vessels and spleen producing IL-6 andIL-1β are responsible for an increase in the amount of Bregs associatedwith arthritis, while CD4+ splenic T cells producing IL-21 activateBregs in experimental arthritis models." (PMID 30397522, 2018). "This greatly reduced disease incidence shows the potential of the early IL-6/IL-21 combination strategy over single cytokine inhibition in blocking arthritis development, with comparable efficacy as the positive control group receiving TNFα inhibitors." (PMID 28158305, 2017). "In mice treated from the day of immunization with anti-IL-6 and anti-IL-21 treatment on the other hand, clinical arthritis severity based on swelling and redness of the four paws was greatly reduced in comparison with the isotype control group." (PMID 28158305, 2017). "Remarkably, mice treated with the late anti-IL-6R/anti-IL-21 combination therapy show a clear protective effect on arthritis incidence; only 60% of those mice developed arthritis before the end of the study (day 30)." (PMID 28158305, 2017). "We next investigated the in vivo effects of IL-6 and IL-21 pathway blockade on Th17 differentiation and the development of experimental arthritis." (PMID 28158305, 2017). "Overall, this study confirmed the importance of IL-6 and IL-21 during Th17 development in vivo, and showed higher potency of blocking both cytokine pathways above blocking either one in reducing the severity of arthritis." (PMID 28158305, 2017).
Arthritis (continued). "In this regard, Block and Huang made a detailed observation of the roles of IL-21 signaling in immune responses in the K/BxN mouse model of spontaneous arthritis." (PMID 27535236, 2016). "Blocking the IL-21 pathway with IL-21R-Fc fusion protein has been shown to ameliorate the clinical and histologic signs of arthritis and dramatically reduce total IgG1 and inflammatory cytokines levels." (PMID 23176102, 2012). "A recent publication reported that blockade of IL-21 effects with a murine IL-21 receptor Fc fusion protein attenuated disease in both mouse and rat models of arthritis." (PMID 18234077, 2008). "TFh cells may be involved in the pathological process of arthritis through the production of cytokines, such as IL-21, and the modulation of B cell activity." (PMID 40909283, 2025). "In addition, another study in K/BxN mouse described the importance of IL-21, a typical Tfh cytokine in the development of arthritis." (PMID 34638855, 2021). "To test whether increased IL-21 can overcome the attenuating effects of alcohol-exposure on arthritis, we injected IL-21 expressing mini-circle (mc) DNA24 3 days before CII immunization." (PMID 32332730, 2020). "Systemic IL-21 neutralization in arthritis showed only modest, although significant, effects." (PMID 32332730, 2020). "Thus, the rescue of the suppressive effects of ethanol on arthritis by IL-21 seem to be downstream of TFH cells." (PMID 32332730, 2020). "Supporting the anti-inflammatory role of PRL in arthritis, PRL-receptor-null mice exhibited increased joint swelling and higher joint expression of the genes encoding for TNFα, IL-1β, IL-6, IFNγ, IL-17A, IL-21, IL-22, IL-23, and IL-10 when subjected to monoarticular AIA (MAIA)." (PMID 28506283, 2017). "Collectively, these results suggest dual IL-6/IL-21 inhibition may be a more efficacious therapeutic strategy compared to single cytokine blockade to suppress arthritis development." (PMID 28158305, 2017). "Interestingly, arthritis incidence was further reduced when mice were treated with the anti-IL-6R/anti-IL-21 combination therapy, resulting in only 40% of mice developing arthritis." (PMID 28158305, 2017). "The aim of this study was to assess whether combinatorial IL-6/IL-21 blockade would more potently inhibit Th17 development, and be more efficacious in treating arthritis than targeting either cytokine." (PMID 28158305, 2017). "Additionally, anti-IL-6/anti-IL-21 treatment of CIA mice during the arthritis induction phase reduced disease development more potent than IL-6 or IL-21 inhibition alone, as effective as anti-TNF treatment." (PMID 28158305, 2017). "Their observation was made in cell transfer experiments, however, and IL-21 might play an additional role in the spontaneous development of arthritis in K/BxN mice." (PMID 27535236, 2016). "In this context it is of note that serum levels of granzyme B, an acidic protease expressed by cytotoxic T lymphocytes, have been reported to be increased in arthritis and positively correlated with erosive RA, and that IL-21 increases its expression in CD8+ T cells." (PMID 26353115, 2015). "Hence, IL-21 restored arthritis even in the presence of ethanol." (PMID 32332730, 2020). "Interestingly, as opposed to this T cell effect, previous studies showed the reducing effect of IL-21 blockade on arthritis development could be attributed to a defect in B cell development rather than in T cell development in the K/BxN and collagen-induced arthritis (CIA) murine arthritis models." (PMID 28158305, 2017). "Therefore, the purpose of this study was to determine whether IL-6/IL-21 combinatorial pathway blockade has additional inhibitory effects on Th17 differentiation, and more effectively reduces development of T cell-dependent experimental arthritis." (PMID 28158305, 2017).
Arthritis (continued). "More interestingly, we showed a positive linear correlation between the serum IL-21 levels and the VAS for arthritis or the DAS-28-ESR, and SSc patients with moderate–high joint involvement had statistically significantly higher serum IL-21 levels than SSc patients with a DAS28-ESR ≤ 3.2." (PMID 37763102, 2023). "Moreover, the peripheral blood CD21low B cell percentage and serum IL-4 and IL-21 levels were positively correlated with the DAS28-ESR and VAS for arthritis." (PMID 37763102, 2023). "In addition to IL-6, IL-21 and IL-23 can induce STAT3, and both of these compounds take part in arthritis." (PMID 33515210, 2021). "Furthermore, ursolic acid reduced the incidence and severity of CIA-induced arthritis, accompanied by the decreased expression of TNF-α, IL-1β, IL-6, IL-21, and IL-17 in arthritic joints." (PMID 32116720, 2020). "IL-21+TFH cell numbers, however, remained unchanged by alcohol and acetate and also serum IgG or TNP-FICOLL-specific IgG levels remained unchanged overall supporting the data obtained in passive model of arthritis." (PMID 32332730, 2020). "In mice with AIA, absence of IL-6 and IL-21 signaling more strongly reduced Th17 levels and resulted in stronger suppression of arthritis than the absence of either cytokine." (PMID 28158305, 2017). "Regardless of the mechanism of action, a block in IL-21 reduced experimental arthritis development in the majority of reported studies, including the present study." (PMID 28158305, 2017). "Our study shows that alcohol alters the activity of TFH cells by down-regulating key activation nodes such as Bcl6, PD-1 and IL-21, thereby preventing the formation of functional TFH:B cell conjugates and ultimately leading to a decline in autoantibody production and lower incidence of arthritis." (PMID 32332730, 2020). "IL-21 levels were comparable between arthritis positive and negative subjects (p=0.46)." (PMID 23064011, 2012). "Interestingly, neither anti-IL-6R antibodies, nor anti-IL-21 therapy as single treatments could reduce arthritis severity in the severe and progressive collagen-induced arthritis model." (PMID 28158305, 2017).
multiple sclerosis (23 papers, 2009 to 2026). A progressive autoimmune disorder affecting the central nervous system resulting in demyelination. "Spolski and Leonard suggested using IL21 to expand B regulatory cells in vitro prior to adoptive transfer into patients with multiple sclerosis to inhibit inflammatory response." (PMID 37731503, 2023). "It has been reported that IL-21 acts as a pro-inflammatory agent during multiple sclerosis progression and so it has been suggested that IL-21 may promote disease advancement." (PMID 36707891, 2023). "Interestingly, brain samples obtained from human patients with multiple sclerosis showed higher expression of IL-21 and its receptor, supporting a potential role of IL-21 in neurodegenerative diseases." (PMID 32185190, 2020). "IL-21 is also expressed in neurons in the gray matter in multiple sclerosis." (PMID 22030011, 2011). "In multiple sclerosis, an autoimmune disease that involves infiltration of T cells and B cells in parenchymal demyelinating lesions, as well as development of lymphoid aggregates in the meninges, a similarly high frequency of IL-21-producing T cells has been reported." (PMID 30190721, 2018). "While the expression of CXCR5 may differ between cerebrospinal fluid and tissue, these observations raise the possibility that a large portion of the IL-21+ CD4+ T cells in multiple sclerosis may not express CXCR5." (PMID 30190721, 2018).
Crohn disease (21 papers, 2008 to 2025). A gastrointestinal disorder characterized by chronic inflammation involving all layers of the intestinal wall, noncaseating granulomas affecting the intestinal wall and regional lymph nodes, and transmural fibrosis. "Consistent with this notion, dysregulated IL-21 expression is associated with multiple inflammatory conditions, including Crohn's disease, celiac disease and arthritis." (PMID 31867283, 2019). "In a study of Crohn’s disease, IL-17 and IL-21 produced by Th17 cells and T follicular helper cells (Tfh cells) were found to induce the differentiation of IgG4 containing plasma cells." (PMID 41050654, 2025). "Reanalysis of published data sets also revealed an inverse correlation between PRDM1 and IL21 in Crohn’s disease." (PMID 35503415, 2022). "IL-21 is highly produced in human subjects with Crohn's disease and the blockade of the IL-21/IL-21R signaling axis in these patients resulted in reduced production of IFN-γ by mucosal lymphocytes." (PMID 31867283, 2019). "Elevated IL-21 has been observed in the gut of patients with IBD, especially in Crohn's disease (CD), which is thought to be caused by an exaggerated Th1 response against the luminal flora, whereas there are limited data about IL-21 in patients with UC." (PMID 30855475, 2019). "Interleukin-21 (IL-21) is primarily a T cell-derived cytokine; it is upregulated in patients with Crohn's Disease (CD) and could be a potential new therapeutic target in CD." (PMID 29849593, 2018). "Furthermore, IL-21 was detected at high levels in the gut of patients with Crohn’s disease and ulcerative colitis." (PMID 24944624, 2014). "IL-21 expression is enhanced at the site of the involved gut in Crohn's disease." (PMID 22030011, 2011). "For example, in the early stages of Crohn’s disease, macroscopically unaffected neoterminal ileum contained high levels of IFN-γ and IL-21, which are produced by Th1 cells." (PMID 31941937, 2020). "It had been demonstrated that IL-21 is produced by CD4+ but not CD8+ T cells in both Crohn’s disease and ulcerative colitis patients." (PMID 27468819, 2016).
hepatocellular carcinoma (18 papers, 2015 to 2025). A malignant tumor that arises from hepatocytes. "Studies from other groups, as well as ours, have also indicated that IL-21 is closely associated with the pathogenesis of liver fibrosis, liver failure and hepatocellular carcinoma (HCC)." (PMID 28467480, 2017). "More recently, close proximity of intrahepatic CD8+ T cells to Tph-like CD4+ T cells that produced IL-21 and CXCL13 was associated with reversal of exhaustion after immune checkpoint inhibitor blockade in hepatocellular carcinoma." (PMID 40956619, 2025). "These IL-21 expressing CAR-T cells are currently being evaluated in clinical trials for the treatment of hepatocellular carcinoma (HCC) (NCT02932956 and NCT02905188)." (PMID 38090585, 2023). "The combination of IL-2 and IL-21 directly enhanced the cytotoxicity of human γδT cells to hepatocellular carcinoma cells in vitro." (PMID 35747139, 2022). "A new protumorigenic IL-21+ Tfh-like cell subset with a CXCR5−PD-1− BTLA−CD69hi phenotype was identified in hepatocellular carcinoma (HCC)." (PMID 31480382, 2019). "Bio-CS nanomaterials stimulated an immune response in hepatoma cells via increased expression of GM-CSF, IL-21 and Rae-1 markers." (PMID 28938619, 2017). "Local gene transfer of plasmids inducing the expression of IL-21 and soluble PD-1 significantly inhibited the development of H22 hepatocellular carcinomas in syngeneic mice, through the activation of CTL and NK cell responses, production of IL-2 and IFN-γ." (PMID 25961061, 2015). "The use of IL‐21 in solution in the priming of NK cell culture resulted in an improved NK cell proliferation, without compromising cytotoxicity potential or interferon gamma secretion against hepatocellular carcinoma cell lines." (PMID 39865344, 2025). "Additionally, IL-7 and IL-21 promote T cell persistence and memory formation, whereas the co-expression of IL-21 and IL-15 has proven effective at controlling tumor growth in hepatocellular carcinoma models." (PMID 40771804, 2025). "Whether the CXCL13+ cells seen by RNA-seq and IL-21+ T cells detected by flow cytometry represent the same T cell population in hepatocellular carcinoma will be of interest to resolve." (PMID 30190721, 2018). "The chemokine receptor expression on this T cell population (e.g., CXCR5) was not evaluated in this study; however, an independent study of T cell infiltrates in hepatocellular carcinoma identified a prominent IL-21-producing T cell population that accumulates within the peritumoral stroma." (PMID 30190721, 2018). "In a murine model of hepatocellular carcinoma, IL-21 showed synergistic activity with soluble PD-1." (PMID 25961061, 2015). "For example, the hepatocellular carcinoma (HCC) microenvironment is devoid of interleukin (IL) 15 and 21, which are essential for the proper functioning of T-cells, therefore human GPC3-CAR T cells co-expressing IL-15 and IL-21 were very efficient in the treatment of HCC in preclinical models." (PMID 36428480, 2022).